TTYH3 (tweety family member 3)
Description:
Calcium-independent, swelling-dependent volume-regulated anion channel (VRAC-swell) which plays a pivotal role in the process of regulatory volume decrease (RVD) in the brain through the efflux of anions like chloride and organic osmolytes like glutamate (By similarity). Probable large-conductance Ca(2+)-activated chloride channel.
Synonyms: KIAA1691
Tractability: Antibody: UniProt places it where antibodies can reach, with high confidence; its Gene Ontology location is reachable by antibodies, with high confidence; UniProt predicts a signal peptide or a membrane-spanning region. PROTAC: UniProt records ubiquitination sites on it; ubiquitination databases record sites on it; its protein half-life has been measured.
Gene: Protein-coding gene on chromosome 7 (2,631,919 to 2,664,816, forward strand). Ensembl gene ENSG00000136295.
Subcellular location: Cell membrane
Pathways (Reactome):
Transport of small molecules: Stimuli-sensing channels
Gene Ontology:
Molecular function: chloride channel activity; intracellularly calcium-gated chloride channel activity; protein binding; volume-sensitive anion channel activity; calcium ion binding; volume-sensitive chloride channel activity
Biological process: chloride transport; monoatomic ion transmembrane transport; chloride transmembrane transport; L-glutamate transmembrane transport
Cellular component: extracellular exosome; plasma membrane; membrane
Genetic constraint (gnomAD): Loss-of-function variants: 23 observed, 47.65 expected, observed/expected ratio (o/e) 0.48, 90% interval 0.35 to 0.68. The synonymous counts are far from expectation, so gnomAD's model fits this gene poorly and the ratio says little. Missense variants: 768 observed, 614.69 expected, observed/expected ratio (o/e) 1.25, 90% interval 1.18 to 1.33. Synonymous variants: 360 observed, 275.83 expected, observed/expected ratio (o/e) 1.31, 90% interval 1.2 to 1.42.
Homologues: Orthologues: chimpanzee TTYH3 (99% identical), chimpanzee TTYH3 (96% identical), dog TTYH3 (96% identical), mouse Ttyh3 (95% identical), pig TTYH3 (95% identical), guinea pig Ttyh3 (95% identical), rat Ttyh3 (91% identical), rabbit TTYH3 (85% identical), macaque TTYH3 (77% identical), tropical clawed frog ttyh3 (72% identical), zebrafish ttyh3b (71% identical), zebrafish ttyh3a (67% identical), and 3 more. Paralogues in human: TTYH2 (41% identical), TTYH1 (33% identical).
Diseases named in the same sentence as TTYH3 in open-access papers:
TTYH3 is named in the same sentence as 40 diseases in open-access papers, as found by Europe PMC text mining. Sharing a sentence is not in itself a finding about the gene and the disease. The quoted sentences say what the papers report.
gastric cancer (7 papers, 2019 to 2022). A primary or metastatic malignant neoplasm involving the stomach. "A study revealed that the upregulation of the TTYH3 in gastric cancer was associated with shorter survival." (PMID 33997099, 2021). "Bioinformatics analysis has indicated that TTYH3 is overexpressed in gastric cancer and is related to poor prognosis 22; however, its biological function and clinical significance in HCC has never been studied." (PMID 35844789, 2022). "TTYH3 is also upregulated in gastric cancer and was found to be correlated with patient prognosis via bioinformatics analysis." (PMID 35844789, 2022). "TTYH3 is also a large-conductance Ca2+-activated chloride channel whose expression results in poor prognosis in gastric cancer." (PMID 36142409, 2022). "Consistent to the expression pattern of TTYH3 in gastric cancer, TTYH3 presented higher expression in OC cells and tissues in mRNA or protein expression levels compared to normal ovarian cells and tissues." (PMID 34729116, 2021). "In this mining study, we used several online bioinformatic platforms and web tools to systematically analyze the expression, methylation status, mutations and CNAs, correlated genes, and prognostic value of TTYH3 in human gastric cancer." (PMID 31652813, 2019). "We previously reported that TTYH3 is highly expressed in gastric cancer." (PMID 36142409, 2022). "We compared TTYH3 expression in normal and gastric cancer tissues using various databases." (PMID 36142409, 2022). "A high expression of TTYH3 led to poor outcomes in patients with gastric cancer." (PMID 36142409, 2022). "Therefore, this is the first data mining study to predict the possible role of TTYH3 in gastric cancers as it is the only member of the TTYHs which was highly expressed in gastric cancer, based on publicly available gene expression and clinical data." (PMID 31652813, 2019). "TTYH3 expression was higher in gastric cancer tissues than in normal tissues." (PMID 36142409, 2022).
lung carcinoma (4 papers, 2019 to 2025). "The expression of TTYH3, another identified marker, has been associated with poor prognosis and poor response to immunotherapy in lung cancer with high level of expression associated with immune cell infiltration, specifically macrophages and T-reg cells." (PMID 39516397, 2023). "Although its role as an oncogene in lung cancer is established, the implication of TTYH3 in NSCLC metastasis was previously uncertain." (PMID 39930621, 2025). "The comparison of expression level between each type of cancer vs. normal counterpart revealed the upregulation of TTYH3 in gastric, breast, colorectal, esophageal, and lung cancers and in melanoma." (PMID 31652813, 2019).
bladder cancer (3 papers, 2022 to 2024). "Increasingly greater expression of the TTYH3 gene was associated with increasingly worse prognosis of bladder cancer patients." (PMID 36142409, 2022). "For example, TTYH3 has been shown to facilitate bladder cancer through the FGFR1/H‐Ras/A‐Raf/MEK/ERK pathway, and its upregulation promotes EMT in cholangiocarcinoma." (PMID 38827027, 2024). "By observing the behavior of cancer cells in vitro, the migration and invasion ability of TTYH3 knockdown bladder cancer cells were compared with those of scramble-transfected bladder cancer cells." (PMID 36142409, 2022). "The collective findings indicate that bladder cancer cells are regulated by TTYH3 through FGFR1 and the H-Ras/A-Raf/MEK/ERK pathways." (PMID 36142409, 2022). "The mRNA expression of TTYH3 in bladder cancer patients was investigated using various bioinformatics databases." (PMID 36142409, 2022). "In both datasets from different web tools, mRNA expression of TTYH3 was higher in bladder cancer tissues than in normal tissues." (PMID 36142409, 2022). "Using the Oncomine cancer microarray database, the mRNA expression of TTYH3 in two types of bladder cancer, infiltrating BLCA and superficial bladder cancer, was compared with that in a healthy bladder." (PMID 36142409, 2022). "In conclusion, TTYH3 expression is increased in bladder cancer and is related to the aggressive progression of cancer." (PMID 36142409, 2022). "The survival rates according to the increase in TTYH3 gene expression in patients with bladder cancer were compared." (PMID 36142409, 2022). "Our study indicates that TTYH3 regulates tumor proliferation, migration, and invasion and is overexpressed in bladder cancer patients, providing poor outcomes." (PMID 36142409, 2022). "Here, we investigated the correlation between TTYH3 and bladder cancer and revealed the mechanism of its effect on bladder cancer through experimental analyses." (PMID 36142409, 2022). "In the present study, when TTYH3 was knocked down, the expressions of c-Fos and c-Jun decreased, and the abilities to migrate and invade bladder cancer were reduced." (PMID 36142409, 2022). "The collective and individual migration abilities of bladder cancer cells, in which TTYH3 was knocked down, were also determined using wound closure, and transwell migration assays were performed." (PMID 36142409, 2022). "We observed that TTYH3 was significantly upregulated in bladder cancer tissue, compared to adjacent normal tissue." (PMID 36142409, 2022). "To understand the role of TTYH3 in bladder cancer cells, we used a lentiviral TTYH3 knockdown vector to suppress TTYH3 expression in J82 and T24 cells." (PMID 36142409, 2022). "The results demonstrated that the increasingly greater expression of TTYH3 increasingly worsened the prognosis of patients with bladder cancer." (PMID 36142409, 2022). "In patients with BLCA, the elevated TTYH3 levels correlated with poor prognosis in bladder cancer patients." (PMID 36142409, 2022). "Using the UALCAN web tool, we also found a downregulation of the promoter methylation of TTYH3 in bladder cancer tissues." (PMID 36142409, 2022). "TTYH3 knockdown bladder cancer cell lines were constructed by their various cancer properties measured." (PMID 36142409, 2022). "The findings implicate TTYH3 as a potential factor regulating the properties of bladder cancer and as a therapeutic target." (PMID 36142409, 2022). "The invasion ability of bladder cancer cells was reduced in TTYH3 knockdown cells in a basement membrane extract cell invasion assay." (PMID 36142409, 2022). "The expression of TTYH3 and its prognosis in bladder cancer were assessed in vitro and clinically using knockdown cells and bioinformatics web tools, respectively." (PMID 36142409, 2022). "TTYH3 knockdown significantly inhibited the growth, migration, and invasion of bladder cancer cells." (PMID 36142409, 2022).
bladder cancer (continued). "The functions of TTYH3 in bladder cancer cell proliferation, sphere formation, migration, and invasion were also assessed in vitro." (PMID 36142409, 2022). "We investigated the mechanism of TTYH3 in bladder cancer through in vitro experiments and analysis of clinical data using bioinformatics tools." (PMID 36142409, 2022). "To confirm that TTYH3 expression affects bladder cancer function, we performed some in vitro assays in bladder cancer cell lines." (PMID 36142409, 2022). "The expression of TTYH3 was higher in bladder cancer cell lines than in other cancer cell lines and higher in cell lines derived from high-grade transitional cell carcinomas, such as T24 and J82 cell lines." (PMID 36142409, 2022). "Because of the low promoter methylation of TTYH3, its expression of TTYH3 in bladder cancer tissues is predicted to be higher than that in normal tissues." (PMID 36142409, 2022). "The team of Polash Kumar Biswas showed that the expression of TTYH3 was higher in bladder cancer and GC than in normal tissues, which was significantly associated with reduced patient survival, suggesting that TTYH3 may be a therapeutic target." (PMID 37370118, 2023). "We knocked down TTYH3 using lentivirus in the J82 and T24 bladder cancer cell lines." (PMID 36142409, 2022). "We investigated the role of TTYH3 as a cancer-promoting factor in bladder cancer." (PMID 36142409, 2022). "The migration ability of the bladder cancer cells was reduced upon TTYH3 knockdown." (PMID 36142409, 2022). "We observed changes in the ERK-mediated H-Ras pathway in TTYH3 knockdown bladder cancer cells." (PMID 36142409, 2022). "Further studies are needed to determine whether TTYH3 promoter methylation affects TTYH3 expression and prognosis in bladder cancer." (PMID 36142409, 2022). "Various web-based tools, such as UALCAN, GEPIA2, Oncomine, and PrognoScan, were used to determine whether TTYH3 gene expression affects cancer progression in bladder cancer patients." (PMID 36142409, 2022). "Moreover, migration and invasion abilities were reduced in TTYH3 knockdown bladder cancer cell lines." (PMID 36142409, 2022). "Furthermore, we present the possibility that TTYH3 can act as a predictive biomarker in bladder cancer patients and can be used as a therapeutic target." (PMID 36142409, 2022). "Therefore, we investigated the relationship between TTYH3 expression and prognosis in bladder cancer patients." (PMID 36142409, 2022). "Recent studies have reported the role of the TTYH3/MK5 axis in regulating GSK‐3β/β‐catenin signaling in hepatocellular carcinoma, and its involvement in bladder cancer progression through the FGFR1/H‐Ras/A‐Raf/MEK/ERK pathway." (PMID 38827027, 2024). "The findings indicate that the expression of TTYH3 may affect the phosphorylation of FGFR1, inhibit H-Ras/A-Raf/MEK signaling, and inhibit the proliferation of bladder cancer cells." (PMID 36142409, 2022). "Previous studies have shown that TTYH3 is overexpressed in certain cancers and is related to a poor prognosis of cancer; however, its biological function and clinical significance in bladder cancer has never been studied." (PMID 36142409, 2022).
glioma (3 papers, 2019 to 2021). A benign or malignant brain and spinal cord tumor that arises from glial cells (astrocytes, oligodendrocytes, ependymal cells). "Only one analysis revealed the downregulation of TTYH3 expression in brain and central nervous system cancer." (PMID 31652813, 2019). "Interestingly, across gliomas and brain cancers, TTYH3 shows consistent upregulation in pathological cells and tissue." (PMID 34262434, 2021). "However, TTYH3 consistently demonstrated upregulation in glioma tissues." (PMID 34262434, 2021). "Furthermore, glioblastomas with 1p/19q chromosome arms codeletions (associated with diminished glioma propagation and impaired tumor microtube formation and function) show TTYH1 and TTYH2 downregulation and TTYH3 upregulation compared to 1p/19q non-codeleted gliomas." (PMID 34262434, 2021).
breast carcinoma (2 papers, 2021 to 2022). "The upregulation of TTYH3 in breast cancer-associated cells is consistent with the upregulation reported in brain and colon cancers." (PMID 34262434, 2021). "In contrast with TTYH1, TTYH2 and TTYH3 have only been studied in breast cancer through RNA-Seq and microarray analyses with TTYH2 showing downregulation and TTYH3 showing upregulation in breast cancer-associated cells and tissues." (PMID 34262434, 2021).
cholangiocarcinoma (2 papers, 2022 to 2024). A carcinoma that arises from the intrahepatic biliary tree (intrahepatic cholangiocarcinoma) or from the junction, or adjacent to the junction, of the right and left hepatic ducts (hilar cholangiocarcinoma). "For example, in cholangiocarcinoma, high expression of TTYH3 accelerated ETM transformation and promoted malignant behavior of cholangiocarcinoma cells." (PMID 35935583, 2022).
colon cancer (2 papers, 2021 to 2022). "TTYH3 demonstrated upregulation in association with colon cancer, consistent with the TTYH3 upregulation pattern in brain cancers." (PMID 34262434, 2021). "In contrast with the functional studies conducted on TTYH2 in colon cancer, TTYH1 and TTYH3 have only been studied in colon cancer through gene expression assays." (PMID 34262434, 2021). "According to gene expression assay, TTYH3 is upregulated in brain and colon cancer." (PMID 35844789, 2022).
colorectal cancer (2 papers, 2022 to 2024). A primary or metastatic malignant neoplasm that affects the colon or rectum. "In ovarian cancer, cervical cancer, and colorectal cancer, elevated expression of TTYH3 also predicted poor prognosis." (PMID 35935583, 2022).
hepatocellular carcinoma (2 papers, 2024 to 2025). A malignant tumor that arises from hepatocytes. "have reported that TTYH3 can impact EMT through GSK3‐β/β‐catenin pathway in hepatocellular carcinoma." (PMID 38827027, 2024).
acute leukemia (1 paper, 2023). A clonal (malignant) hematopoietic disorder with an acute onset, affecting the bone marrow and the peripheral blood. "We also obtained the interacting partners of AGAP3 from the STRING database, of which TTYH3, which has a significant effect on survival probabilities in AML samples (p-value = 0.03), was significantly upregulated in acute leukemia samples." (PMID 37113989, 2023).
Batten disease (1 paper, 2025). "A recent paper exploring the proteomic changes in microglia with another LSD, Batten disease caused by loss of CLN3, identify similar changes to those seen here, including increased TTYH3, PTTG1IP, LAMTOR3, PSAP, STARD3NL, TSPAN7, TMEM192 and NPC1." (PMID 40608809, 2025).
cystic fibrosis (1 paper, 2021). Autosomal recessive disorder caused by pathogenic variants in the CFTR gene (cystic fibrosis transmembrane conductance regulator), which encodes a chloride and bicarbonate channel expressed in epithelial cells, and follow the diagnosis criteria. "Additionally, TTYH3’s involvement in cystic fibrosis is suggested by strong downregulation of mTTYH3 in intestines of cftrtumor microtubule1Cam mice, although mTTYH3 is not downregulated in cftrTgH(neoim)Hgu mice with a weaker cystic fibrosis phenotype." (PMID 34262434, 2021).
cytomegalovirus infection (1 paper, 2022). A herpesvirus infection caused by Cytomegalovirus. "Kyoto Encyclopedia of Genes and Genomes (KEGG) pathway analysis revealed regulation of the actin cytoskeleton, cytomegalovirus infection, SNARE interaction, and mitogen-activated protein kinase (MAPK) signaling pathway functions when TTYH3 co-expressed genes were highly expressed." (PMID 36142409, 2022).
glioblastoma (1 paper, 2022). The most malignant astrocytic tumor (WHO grade IV). "In addition to its individual functions, TTYH3 may also promote tumorigenesis by fusion with BRAF serine/threonine kinase (TTYH3-BRAF fusion protein) in glioblastoma, histiocytic sarcoma, and thyroid carcinoma 36-38." (PMID 35844789, 2022).
osteosarcoma (1 paper, 2021). A usually aggressive malignant bone-forming mesenchymal neoplasm, predominantly affecting adolescents and young adults. "Again, TTYH3 upregulation in osteosarcoma tissues and cells is consistent with TTYH3 upregulation patterns seen in other cancers." (PMID 34262434, 2021). "In contrast with TTYH2, TTYH1 and TTYH3 have only been studied in osteosarcoma through microarray and RNA-Seq experiments showing TTYH1 downregulation and TTYH3 upregulation." (PMID 34262434, 2021).
testicular cancer (1 paper, 2019). A primary or metastatic malignant neoplasm that affects the testis. "In the GENT database, analyzed using the U133Plus2 platform, TTYH3 expression was upregulated in certain cancer types, including bladder, breast, colon, lung, pancreatic, stomach, ovarian, and testicular cancers." (PMID 31652813, 2019).